SNORD115-46 (small nucleolar RNA, C/D box 115-46)
Synonyms: HBII-52-46
Gene: Small nucleolar RNA gene on chromosome 15 (25,266,591 to 25,266,661, forward strand). Ensembl gene ENSG00000276844.
Gene Ontology:
Biological process: RNA processing
Cellular component: nucleolus
Homologues: Orthologues: chimpanzee SNORD115 (94% identical), macaque SNORD115 (92% identical), rabbit SNORD115 (69% identical), pig SNORD115 (68% identical), rat LOC120100287 (68% identical), dog SNORD115 (62% identical). Paralogues in human: SNORD115-34 (76% identical), SNORD115-39 (76% identical), SNORD115-6 (76% identical), SNORD115-8 (76% identical), SNORD115-11 (75% identical), SNORD115-2 (75% identical), SNORD115-20 (75% identical), SNORD115-29 (75% identical), SNORD115-32 (75% identical), SNORD115-36 (75% identical), SNORD115-38 (75% identical), SNORD115-42 (75% identical), and 37 more.